ORC1 (origin recognition complex subunit 1)
Description:
Component of the origin recognition complex (ORC) that binds origins of replication. DNA-binding is ATP-dependent. The DNA sequences that define origins of replication have not been identified yet. ORC is required to assemble the pre-replication complex necessary to initiate DNA replication.
Synonyms: ORC1L; PARC1; HSORC1
Tractability: Small molecule: a structure with a bound ligand is known. PROTAC: ubiquitination databases record sites on it.
Gene: Protein-coding gene on chromosome 1 (52,372,010 to 52,404,471, reverse strand). Ensembl gene ENSG00000085840.
Subcellular location: Nucleus
Subcellular location (Human Protein Atlas): Nucleoplasm
Pathways (Reactome):
DNA Replication: Activation of the pre-replicative complex; Assembly of the ORC complex at the origin of replication; Assembly of the pre-replicative complex; CDC6 association with the ORC:origin complex; Orc1 removal from chromatin
Cell Cycle: Activation of ATR in response to replication stress; E2F-enabled inhibition of pre-replication complex formation; G1/S-Specific Transcription
Gene Ontology:
Molecular function: protein binding; DNA binding; DNA replication origin binding; ATP binding; ATP hydrolysis activity; chromatin binding
Biological process: DNA replication initiation; mitotic DNA replication checkpoint signaling
Cellular component: chromosome, telomeric region; nuclear origin of replication recognition complex; nucleoplasm; origin recognition complex; cytosol; nucleus
Genetic constraint (gnomAD): Loss-of-function variants: 56 observed, 97.24 expected, observed/expected ratio (o/e) 0.58, 90% interval 0.46 to 0.72. The upper end of that interval is the gene's LOEUF score, 0.72, which puts it in group 2 of 6, group 1 being the genes least tolerant of losing a copy. Missense variants: 975 observed, 1,118.2 expected, observed/expected ratio (o/e) 0.87, 90% interval 0.83 to 0.92. Synonymous variants: 381 observed, 426.48 expected, observed/expected ratio (o/e) 0.89, 90% interval 0.82 to 0.97.
Homologues: Orthologues: chimpanzee ORC1 (98% identical), macaque ORC1 (95% identical), dog ORC1 (81% identical), pig ORC1 (79% identical), rabbit ORC1 (78% identical), guinea pig ORC1 (75% identical), rat Orc1 (69% identical), mouse Orc1 (66% identical), tropical clawed frog orc1 (53% identical), zebrafish orc1 (50% identical), Drosophila melanogaster Orc1 (33% identical), Caenorhabditis elegans orc-1 (20% identical). Paralogues in human: CDC6 (17% identical).
Diseases named in the same sentence as ORC1 in open-access papers:
ORC1 is named in the same sentence as 56 diseases in open-access papers, as found by Europe PMC text mining. Sharing a sentence is not in itself a finding about the gene and the disease. The quoted sentences say what the papers report.
Meier-Gorlin syndrome (12 papers, 2012 to 2023). "Correct targeting of ORC1 to the centrosome is crucial as revealed by deficiencies observed in patients of the Meier-Gorlin syndrome that harbor mutations in the ORC1 gene." (PMID 31990293, 2020). "A form of dwarfism known as Meier-Gorlin syndrome (MGS) is caused by recessive mutations in one of six different genes (ORC1, ORC4, ORC6, CDC6, CDT1, and MCM5)." (PMID 29036220, 2017). "The Cyclin E-CDK2 kinase inhibitory activity is compromised by ORC1 Meier-Gorlin syndrome mutations that also alter the interaction between ORC1 and histone H4K20me2." (PMID 27458800, 2016). "Interestingly, although there is no known data on the phenotypic effect of mutating the equivalent residue in human Orc4 (Arg205), mutation of the analogous residue in Orc1 (Arg666, to Trp) has been linked to Meier-Gorlin syndrome." (PMID 34036936, 2021). "Strikingly, a mutation found in patients with Meier-Gorlin syndrome maps to a highly-conserved C-terminal segment in Orc6, destabilizing the interaction of Drosophila and human Orc6 with both Orc3 alone and with the core Orc1–5 subcomplex." (PMID 24137536, 2013). "Mutations in ORC1, ORC4, ORC6, CDT1, and CDC6, which encode proteins required for DNA replication origin licensing, cause Meier-Gorlin syndrome (MGS), a disorder conferring microcephaly, primordial dwarfism, underdeveloped ears, and skeletal abnormalities." (PMID 23516378, 2013). "Recently, mutations in genes encoding ORC1, ORC4, ORC6, CDT1, and CDC6 were identified in patients displaying Seckel syndrome (SS) and/or Meier-Gorlin syndrome (MGS)." (PMID 23516378, 2013). "Meier-Gorlin syndrome (MGS) is caused by mutations in components of the prereplication and pre-initiation DNA replication complexes (ORC1, ORC4, ORC6, CDT1, CDC6, GMNN, CDC45), which license replication origins and mediate loading and functioning of the replication fork helicase." (PMID 28630177, 2017). "Additionally, mutations in key components involved in initiation of DNA replication, such as ORC1, ORC4, ORC6, CDT1, CDT6, and CDC45, have been reported to be the cause of Meier-Gorlin syndrome, a primordial dwarfism syndrome." (PMID 28915237, 2017).
Hyperornithinemia (6 papers, 2015 to 2025). Increased concentration of ornithine in the blood. "Variants in SLC25A15 produce a disorder of the urea cycle, hyperornithinemia-hyperammonemia-homcitrulluria, due to reduce transport of ornithine by the carrier ORC1." (PMID 33426505, 2020). "The importance of ORC1 transport functions in human metabolism is underlined by HHH syndrome (hyperornithinemia-hyperammonemia-homocitrullinuria, OMIM 212138), which is caused by mutations in the SLC25A15 gene encoding ORC1." (PMID 31510000, 2019). "ORC1 deficiency reduces the mitochondrial availability of ornithine, which increases in the cytosol causing hyperornithinemia." (PMID 25874378, 2015). "ORC1 deficiency also causes the build-up of ornithine in the cytosol and, subsequently, hyperornithinemia, increased levels of polyamines (which originate from cytosolic ornithine), and a secondary creatine deficiency, due to arginine-glycine amidotransferase inhibition by an excess of ornithine." (PMID 32340404, 2020). "Dysfunction in ORC1 results in the accumulation of ornithine in the cytosol, leading to hyperornithinemia." (PMID 40710547, 2025). "Mutations in the ORC1 gene, SLC25A15, have been identified to cause hyperornithinemia, hyperammonemia, and homocitrillinuria (HHH) syndrome in more than 100 patients, the majority of which lives in Canada, Italy, or Japan." (PMID 32340404, 2020). "Hyperornithinemia-hyperammonemia-homocitrullinuria (HHH) syndrome is a rare autosomal recessive urea cycle disorder resulting from a deficiency in the SLC25A15 gene, which encodes ornithine carrier 1 (ORC1)." (PMID 40710547, 2025).
breast carcinoma (5 papers, 2010 to 2023). "In breast cancer, ORC1 mutations were found in 1% of samples." (PMID 37029129, 2023). "Then we performed some analysis of ORC1 protein phosphorylation levels in three tumors, including breast cancer, ovarian cancer and colon cancer." (PMID 37833711, 2023). "Compound 1 suppressed luciferase reporter gene expression driven by the HBO1 (histone acetyltransferase binding to ORC1) gene promoter in human breast cancer MCF7 cells." (PMID 35566260, 2022). "Here, we investigated whether Cdc6, Cdt1 or Orc1 also confer prognostic value to breast cancer patients." (PMID 28428557, 2017). "HBO1 (histone acetyltransferase binding to ORC1) is a histone acetyltransferase (HAT) which could exert oncogenic function in breast cancer." (PMID 21040551, 2010). "Since Cdc6, Cdt1 and Orc1 work cooperatively with MCM2-7 to initiate DNA replication, we have investigated whether there are associations between the numbers of overexpressed MCM2-7 genes and expression of these three genes in breast cancer specimens." (PMID 28428557, 2017). "Since Cdc6, Cdt1 and Orc1 work cooperatively with MCM2-7 to initiate DNA replication, in our current study we have investigated whether there are associations between these three genes and clinicopathological parameters or expression of MCMs in breast cancer." (PMID 28428557, 2017). "There was also a significant positive correlation between Orc1 expression and number of MCM2-7 genes expressed at a high level in breast cancer specimens (spearman’s rank test, r = 0.349, p < 0.001)." (PMID 28428557, 2017). "HBO1, a histone acetyltransferase that binds to the origin recognition complex 1 (ORC1), is highly expressed in carcinomas of the testis, ovary, breast, stomach/esophagus, and bladder, and is known to promote cell proliferation in bladder and breast cancers." (PMID 35566260, 2022). "However, since Cdc6, Cdt1 and Orc1 all play an important role in DNA replication licensing, the reasons for Orc1 mRNA expression not being a prognostic factor in breast cancer may be worth further investigation." (PMID 28428557, 2017).
Hyperammonemia (5 papers, 2019 to 2023). An increased concentration of ammonia in the blood. "In affected patients, ORC1 deficiency reduces the rate of the urea cycle leading to hyperammonemia, a typical feature of most UCD." (PMID 35711415, 2022). "ORC1 deficiency reduces the rate of the urea cycle and hence leads to hyperammonemia, similarly to other genetic diseases associated with the urea cycle and ammonia-related metabolism (including AGC2 deficiency, Section 3.7)." (PMID 32340404, 2020). "Mutations in the solute carrier family 25 member 15 (SLC25A15) gene, which encodes for ORC1, are causative of the rare autosomal recessive urea cycle disorder (UCD) called hyperornithinemia–hyperammonemia–homocitrullinuria (HHH) syndrome (OMIM 238970)." (PMID 35711415, 2022).
microcephaly (5 papers, 2013 to 2025). A congenital or acquired developmental disorder in which the circumference of the head is smaller than normal for the person's age and sex. "For example, ORC1 is involved in centrosome homeostasis, and it has been proposed that deregulation of centrosome copy numbers by MGS variants in the IDR of ORC1 contributes to microcephaly and the more severe growth defects in these patients." (PMID 41448435, 2025). "Mutation in ORC1 can cause growth retardation, microcephaly, and short stature (OMIM:224690), which can explain part of the phenotype of the case." (PMID 33157955, 2020). "In patients with a severe short stature and/or microcephaly, starting with the analysis of ORC1 and ORC4 should be considered, since mutations in these two genes are associated with a significantly shorter stature and smaller head circumference than mutations in the other genes." (PMID 26381604, 2015). "Mutations in ORC1 and ORC4 appear to cause a more severe short stature and microcephaly than mutations in other genes." (PMID 26381604, 2015). "Patients with ORC1 and ORC4 mutations appear to have the most severe short stature and microcephaly." (PMID 26381604, 2015). "However, the fact that deficiency in ORC1 also impairs centrosome stability and the close correlation between centrosomal defects and microcephaly, raised the possibility that additional impacts of licensing deficiency might contribute to the clinical features observed in patients." (PMID 23516378, 2013). "Three genes in the region: ORC1, SCP2, DAB1, may be candidates for the main phenotypes observed in our patient such as short stature, microcephaly, growth retardation, leukoencephalopathy and DD/ID." (PMID 33157955, 2020).
primordial dwarfism (5 papers, 2012 to 2023). "The first individuals identified with biallelic variants in ORC1 have a generalised primordial dwarfism." (PMID 37059840, 2023). "In considering the two originally described cohorts of individuals with variants in ORC1 (the generalised primordial dwarfism versus MGORS), individuals with MGORS tend to have at least one variant that is predicted to lower ORC1 protein levels, such as splicing, frameshift, or genomic deletions." (PMID 37059840, 2023).
colon cancer (4 papers, 2020 to 2023). "Phosphorylation levels of T375 in OV and S311 in colon cancer ORC1 protein were found to be significantly increased by using the CPTAC dataset from the UALCAN database." (PMID 37833711, 2023). "ORC1 is a protein-coding gene, which is overexpressed in colon cancer." (PMID 32193399, 2020).
glioma (4 papers, 2023 to 2024). A benign or malignant brain and spinal cord tumor that arises from glial cells (astrocytes, oligodendrocytes, ependymal cells). "In glioma, ORC1 overexpression could promote its malignant progression by activating the ERK/JNK signaling pathway." (PMID 37005685, 2023). "It has been reported that ORC1 may become a new prognostic marker for glioma by activating the ERK/JNK signaling pathway." (PMID 36941564, 2023). "Recent literature has suggested that ORC1 can activate the ERK and JNK signaling pathways to enhance proliferation and metastasis in glioma." (PMID 36205357, 2023).
cervical cancer (3 papers, 2019 to 2023). A primary or metastatic malignant neoplasm involving the cervix. "Although our study showed the impacts of XIST on cervical cancer progression through miR-140-5p/ORC1 axis, there were still some deficiencies remained to improve." (PMID 30858762, 2019). "Overexpression of ORC1 mediated by the lncRNA XIST/miR‐140‐5p axis promotes the progression of cervical cancer." (PMID 36205357, 2023). "MiR-140-5p was down-regulated but XIST and ORC1 were up-regulated in cervical cancer tissues and cell lines." (PMID 30858762, 2019). "Our study indicated the effects of XIST/miR-140-5p/ORC1 axis on the progression of cervical cancer which will shed new light on epigenetic diagnostics and therapeutics in cervical cancer." (PMID 30858762, 2019). "QRT-PCR results also indicated that ORC1 expression was ubiquitously increased in cervical cancer tissues and cell lines (HeLa and C33A)." (PMID 30858762, 2019). "We designed and conducted experiments in vitro and in vivo for understanding the XST1 function on the development of cervical cancer along with the regulating mechanism through miR-140-5p/ORC1." (PMID 30858762, 2019). "Then, the expression of XIST, miR-140-5p, and ORC1 were detected using qRT-PCR and western blot in both tissues and cervical cancer cell lines (Hela and C33A) to verify the bioinformatics analyses results." (PMID 30858762, 2019). "To further understand the role of ORC1 in cervical cancer, we designed siRNAs specifically targeting ORC1 (si-ORC1-1, si-ORC1-2), and the result of qRT-PCR showed si-ORC1-2 had the best effect for knockdown the expression ORC1, so it was used in the next experiments." (PMID 30858762, 2019). "Moreover, we carried a further exploration of the mechanism of XIST/miR-140-5p axis including the targeting gene ORC1, and provided a new therapeutic method for cervical cancer." (PMID 30858762, 2019). "And the results of cell apoptosis analysis were consistent with the previous experiments, si-ORC1 could significantly promote the apoptosis rate of cervical cancer cells, and miR-140-5p inhibitor and XIST could offset the role of si-ORC1." (PMID 30858762, 2019). "Besides, we found the targeting relationship between miR-140-5p and ORC1, and related cell experiments further proved that XIST could regulate ORC1 by targeting miR-140-5p to affect the progress of cervical cancer." (PMID 30858762, 2019).
colorectal cancer (3 papers, 2021 to 2025). A primary or metastatic malignant neoplasm that affects the colon or rectum. "Colorectal samples in the TCGA cohort were grouped into high-expressed and low-expressed samples based on the median of CDC6 and ORC1 expression, and the Tide algorithm was conducted to investigate immunotherapy response in colorectal cancer samples." (PMID 37945594, 2023). "According to EpiFactor, the CDC6 and ORC1 genes significantly induce epigenetic modifications affecting gene expression in colorectal cancer." (PMID 37945594, 2023). "Chromatin remodeling or acetylation in CDC6/ORC1 may delay DNA replication and promote the development of colorectal cancer." (PMID 39963131, 2025). "Subsequently, in human colorectal carcinoma cell line HCT116, ORC1, and ORC2 were reported to be non-essential for cell proliferation." (PMID 33522487, 2021).
lung adenocarcinoma (3 papers, 2023 to 2025). A carcinoma that arises from the lung and is characterized by the presence of malignant glandular epithelial cells. "At the mRNA level, TCGA data indicated that ETV4, MCM2/4/5/10, and ORC1 mRNA levels were all significantly upregulated in 515 lung adenocarcinoma (LUAD) and 503 lung squamous cell carcinoma (LUSC) compared with normal lung tissue." (PMID 40548893, 2025). "NDC80, CENPL, ORC1, CENPN, CCNE1, and CCNB2 were significantly upregulated in the TCGA cohort as well as in the 18 pairs of lung adenocarcinoma patient samples, and high expression was significantly associated with poor prognosis in lung adenocarcinoma." (PMID 37123398, 2023). "Then we studied the ORC1 protein levels in different tumors in UALCAN database, the available tumor data were BRCA, Kidney renal clear cell carcinoma (KIRC), Uterine Corpus Endometrial Carcinoma (UCEC), and Lung adenocarcinoma (LUAD)." (PMID 37833711, 2023).
prostate carcinoma (3 papers, 2014 to 2020). A carcinoma that arises from epithelial cells of the prostate gland. "In our study, MLN4924 caused accumulation of WEE1/p21/p27, CDT1/ORC1 and NOXA/BIK, which were associated with MLN4924-IR-enhanced G2 cell-cycle arrest, DNA damage and apoptosis in prostate cancer cells." (PMID 27224919, 2016). "Young indicated that because ORC1 was significantly upregulated after irradiation for 6 and 24 hours in PC-3 cells, ORC1 and other DNA repair candidates may be potential targets for radiation sensitization and serve as predictive biomarkers for prostate cancer." (PMID 32194798, 2020).
ciliopathies (2 papers, 2021). "An intriguing connection between MGS and ciliopathy is based on the observation that depletion of ORC1, ORC4, ORC6, CDT1 and CDC6 leads to reduced primary cilia formation." (PMID 33477564, 2021). "A number of proteins, such as fanconi-associated nuclease 1 (FAN1), origin recognition complex subunit 1 (ORC1), envelope glycoprotein gp160 (VCP) and ATM interactor (ATMIN), are DDR proteins that have been implicated in ciliopathies." (PMID 34828368, 2021). "When fibroblasts were depleted for ORC1, ORC4, ORC6, CDT1 and CDC6, primary cilia formation was impaired, suggesting that MGS symptoms might constitute a ciliopathy." (PMID 33477564, 2021).
cutaneous melanoma (2 papers, 2023). A primary melanoma arising from atypical melanocytes in the skin. "ORC1 missense mutations were present in the TCGA PanCancer Atlas with a variable frequency (between 0.2 and 5.5%), the tumour types with the highest frequencies were endometrial cancers and cutaneous melanoma." (PMID 37029129, 2023). "The expression of ORC1 increased with the progression of the tumors in Adrenocortical carcinoma (ACC) and LUAD, while the expression of ORC1 decreased with the progression of the tumors in OV and Skin Cutaneous Melanoma (SKCM)." (PMID 37833711, 2023).
gastric cancer (2 papers, 2021 to 2024). A primary or metastatic malignant neoplasm involving the stomach. "The expression of GAMT was considerably down-regulated in gastric cancer tissues when compared to normal gastric tissues, while the expression of ORC1, CNGB3, and SERPINE1 was significantly up-regulated in gastric cancer tissues." (PMID 38880869, 2024). "The four nucleotide metabolism-related genes that make up NMRI (GAMT, ORC1, CNGB3, and SERPINE1) were verified in an external dataset and are a valid predictor of prognosis for patients with gastric cancer." (PMID 38880869, 2024).
hepatocellular carcinoma (2 papers, 2020 to 2023). A malignant tumor that arises from hepatocytes. "In previous studies, the heterohexameric complex composed of ORC1‐6 has been systematically analyzed in hepatocellular carcinoma." (PMID 36205357, 2023). "In hepatocellular carcinoma, ORC1, 5, and 6 are novel biomarkers for diagnosis and prognosis." (PMID 36205357, 2023).